CD86 (CD86 molecule)
Diseases named in the same sentence as CD86 in open-access papers (continued):
Sharing a sentence is not in itself a finding about the gene and the disease.
ischemic stroke (10 papers, 2018 to 2025). A stroke disorder caused by obstruction of blood flow to the brain, due to thrombotic (local blood clot formation) or embolic (due to a blood clot or other material traveling from another site) event. "CD86-expressing M1 macrophage/microglia is known to be associated with degenerating lesion upon ischemic stroke." (PMID 35887140, 2022). "Compared to the control group, the basal expression of the Cd86 gene showed an increasing trend with an increase in the onset time of ischemic stroke, exhibiting the most pronounced elevation in the MCAO_12 h group (p < 0.01)." (PMID 40520774, 2025). "The predominance of p21+CD86+ M1 microglia in both mice and human ischemic brains highlights their potential role in the inflammatory response following ischemic stroke." (PMID 40585759, 2025). "In the context of ischemic stroke, we identified detrimental p21+CD86+ microglia in the infarct region, providing a novel therapeutic target." (PMID 40585759, 2025). "Single-gene GSEA revealed that the identified signature genes (Pip5k1c, Nlgn2, Fzd2, Cd86, Agpat1, and Degs2) converge on neuroinflammatory and apoptotic pathways critical in ischemic stroke pathogenesis." (PMID 40520774, 2025). "Expression levels (FPKM values) of CD16, CD32, CD86 and CD11b were increased at D1 and peaked at D14 after ischemic stroke." (PMID 29896414, 2018). "The results demonstrated that, in comparison to the control group, the expression of Pip5k1c, Nlgn2, Fzd2, Cd86, Agpat1, and Degs2 showed a downward trend with an increase in the onset time of ischemic stroke, and the decrease was most significant in the MCAO_12 h group (p < 0.01)." (PMID 40520774, 2025). "Taken altogether, these results demonstrate that IRG1−/− MCAO mice exhibit elevated MG activation, displayed with increased CD68H and CD86+ MG as well as Iba1+ cells in the ischaemic brain, compared to WT MCAO mice, suggesting IRG1 deficiency aggravates MG activation in ischaemic stroke." (PMID 34557667, 2021). "With regard to inflammatory responses, an overall increased number of CD86+ cells was detected in males 3 days after HI, which is in line with previous work in a model of neonatal ischemic stroke, demonstrating an increased pro-inflammatory profile in myeloid cells, isolated from male mice." (PMID 34772426, 2021). "CD86 was increased at D1 and peaked at D14 after ischemic stroke." (PMID 29896414, 2018). "These novel findings suggest that micro‐Exo can effectively target and accumulate in CD86‐positive microglia in ischemic regions, offering a promising strategy for enhancing the therapeutic efficacy of exosome‐based senolytic delivery treatments for ischemic stroke." (PMID 40585759, 2025). "In the present study, our findings revealed that IFNβ attenuated tPA-upregulated inflammatory molecules, CD86, IL-1α, and IL-1β, and promoted anti-inflammatory molecules, Arg1 and CD206, in MG during the acute phase of ischemic stroke." (PMID 37063896, 2023). "To explore the effect of 4-EG on MG activation in ischemic stroke, we measured the expression of maturation markers, CD68 and CD86, on MG." (PMID 35860274, 2022). "Indeed, when we analysed the ischaemic brain of WT and IRG1−/− MCAO mice, we found increased CD68+ MG and CD86+ MG as well as elevated Iba1+ cells in the ischaemic brain of IRG1−/− MCAO mice compared to WT MCAO mice, demonstrating IRG1 deficiency promotes MG activation in ischaemic stroke." (PMID 34557667, 2021). "Previous studies have demonstrated that newly repopulated microglia had reduced expression of inflammatory markers (e.g., IL-1β, IL-6, TNF-α and CD86), and upregulation of neuroprotective factors (e.g., CD206, TGF-β, and IL-10) in response to ICH ischemic stroke in ageing." (PMID 40777042, 2025).
liver fibrosis (10 papers, 2013 to 2025). "However, studies have reported that HCV-infected patients show overexpression of memory B-cells, with memory B-cell CD86 levels being associated with advanced liver fibrosis in CHC." (PMID 38893714, 2024). "Expression of the CD86 activation marker on memory B cells was found to be significantly elevated in patients with advanced liver fibrosis (P = 0.0155)." (PMID 23840845, 2013). "In conclusion, we have shown that memory B cells, and generally not naive B cells, are activated in chronic HCV infections and that the expression of memory B cell CD86 correlates with advanced liver fibrosis." (PMID 23840845, 2013). "However, host’s memory B cells expressed more in CHC and memory B cell CD86 related to the advanced liver fibrosis in CHC." (PMID 35560166, 2022). "M1 macrophages represent high expression of CD86, CD68, and iNOS, and secrete the pro-inflammatory factors such as TNF-α, IL-6, and ROS, that exacerbate the hepatic inflammation and tissue injury and promote the development of hepatic fibrosis." (PMID 41375167, 2025). "Here, we found significantly decreased M1 (CD86) and mildly, but not significantly, decreased M2 macrophages in our mouse models of hepatic fibrosis." (PMID 38434258, 2024). "Then we analyzed the number of CD86+ and CD206+ macrophages in liver tissues and found that GFAPMyD88−/− mice exhibited a reduction in the M1-like phenotype and an increase in the M2-like phenotype compared to that in control mice with liver fibrosis." (PMID 35484116, 2022). "In mice identified molecules include liver fibrosis A-3/CD58, ICAM-1/CD54, and B7-2/CD86." (PMID 26339640, 2015). "Again, the yield of CD11c+CD80+, CD11c+CD86+cells did not vary between hepatic NPCs harvested from IDO1−/− fibrotic mice, or WT fibrotic mice and knock out of IDO1 did not influence the expression levels of CD80 and CD86 on hepatic CD11c+DCs during liver fibrosis induced by BDL." (PMID 33414436, 2021).
multiple sclerosis (10 papers, 2014 to 2025). A progressive autoimmune disorder affecting the central nervous system resulting in demyelination. "In these healthy controls, we found that the multiple sclerosis risk allele rs9282641*G is associated with a higher percentage of CD86-positive B cells, primarily in naïve B cells (CD19+CD27−) (P = 5.38 × 10−5)." (PMID 29361022, 2018). "We demonstrate that the local multiple sclerosis risk allele rs9282641*G is associated with a higher percentage of CD86-positive B cells in untreated multiple sclerosis patients and controls." (PMID 29361022, 2018). "Moreover, the expression of CD86 is influenced by local variants correlated with disease susceptibility in the pathogenesis of multiple sclerosis." (PMID 33958982, 2021). "Higher CD86 expression in this B cell subset has previously been associated with multiple sclerosis versus controls with relapse versus remission in multiple sclerosis, and with a phenotype of high neurodegeneration in multiple sclerosis." (PMID 29361022, 2018). "In order to study the effect of multiple sclerosis risk variants mapping within the genes for CD40 (rs4810485) and CD86 (rs9282641) on the surface expression of these co-stimulatory molecules in B cells we collected PBMCs from 68 untreated multiple sclerosis patients and 162 healthy volunteers." (PMID 29361022, 2018). "Previous studies have shown the expression of CD86 in microglia within brain lesions in multiple sclerosis." (PMID 33958982, 2021). "CD86 expression levels on B cells are increased in the CSF compared to the peripheral blood of multiple sclerosis patients, possibly reflecting the high expression levels on plasmablasts." (PMID 29361022, 2018). "As both our genotype data and data on existing treatments indicate cell-subset-specific effects on CD86 expression in multiple sclerosis, in particular related to naïve B cells, such subset-specific effects may underlie this unexpected outcome." (PMID 29361022, 2018). "In this study we assessed surface expression of key co-stimulatory molecules (CD40 and CD86) on B cell subtypes in patients with untreated multiple sclerosis and healthy control subjects, and correlated our findings with genotype at associated SNPs rs4810485 and rs9282641." (PMID 29361022, 2018). "Similarly, the relationship between glial cells activation status evaluated using MHC II, CD86, and CD40 with Treg levels was previously shown in animal model of multiple sclerosis before." (PMID 35571563, 2022). "However, both vitDC and EPDC reduced expression of HLA-DR, CD86, and CD83 in comparison to mDC, both in healthy and multiple sclerosis individuals." (PMID 30792716, 2019). "Although CD80 and CD86 costimulatory molecules play prominent roles in immune regulation and reflect disease status in multiple sclerosis (MS), data in HAM/TSP are lacking." (PMID 24472094, 2014).
Granuloma (9 papers, 2010 to 2025). A compact, organized collection of mature mononuclear phagocytes, which may be but is not necessarily accompanied by accessory features such as necrosis. "We next evaluated the effect of hypoxia on the expression of CD80 and CD86 co-stimulatory molecules and on HLA-DR as these markers are associated with antigen presentation and expressed by epithelioid cells in sarcoidosis granuloma." (PMID 34456926, 2021). "An intense staining for CD4, CD8, and CD86 molecules was observed in NAC-treated granulomas suggesting that reduction in the extent of necrosis and ROI production will maintain the viability of myeloid and lymphoid cells in the granulomas (2L, N, P, R, T)." (PMID 30258443, 2018). "Mature (CD11c+CD86+) DCs are found surrounding granulomas in sarcoid-derived mucosal biopsies, further supporting a role for DCs in airway and parenchymal granuloma formation." (PMID 24339826, 2013). "However, we found that both mDCs in BAL and in granuloma-containing airway biopsies were increased in number and had enhanced expression of maturation marker CD86 in the vicinity of granulomas." (PMID 22513006, 2012). "Finally, immunohistochemical analyses revealed increased numbers of mature CD86+ DCs in granuloma-containing airway mucosal biopsies from sarcoidosis patients." (PMID 22513006, 2012). "By flow cytometric analysis, we found that CD11c+ cells in chronic granulomas had lower expression of MHCII and co-stimulatory molecules CD40, CD80 and CD86, and higher expression of inhibitory molecules PD-L1 and PD-L2 compared to CD11c+ cells from acute granulomas." (PMID 20625513, 2010). "Correlation analysis of positivity rates for CD68, CD86, CD163, and CD206 reveals a significant correlation between CD68 and CD206 in NTMD, primarily expressed in granulomas." (PMID 41189710, 2025).
periodontitis (9 papers, 2021 to 2025). An acute or chronic inflammatory process that affects the tissues that surround and support the teeth. "Subsequently, we investigated macrophage polarization and noted a significant decrease in M2 macrophages (CD68+CD163+) and an increase in M1 macrophages (CD68+CD86+) in periodontitis samples." (PMID 40277454, 2025). "The IHC staining showed that the expressions of PGRN, M1 macrophage-associated markers (CD86 and iNOS), and M2 macrophage-associated markers (TGF-β and CD206) were significantly higher in periodontitis than that in healthy gingiva." (PMID 38689292, 2024). "The percentages of CD83+ and CD86+ cells (DC markers) were significantly higher in response to periodontitis saliva than healthy saliva." (PMID 36207325, 2022). "The Western blotting result showed the increased expression of CD206 (M2Φ maker) and the decreased expression of iNOS and CD86 (M1Φ makers) in the gingiva of the periodontitis mice after treatment with Lipo-RSV." (PMID 34930286, 2021). "Immunofluorescence further demonstrated that macrophage polarization in vivo shifted in response to therapy: periodontitis lesions were dominated by M1 macrophages (high CD86 and IL‐1β, low CD206 and IL‐10), whereas HIPPE‐QU treatment skewed macrophages toward the M2 phenotype." (PMID 41020683, 2025). "Interestingly, periodontitis mice with C3ar-/- genotype exhibited significantly reduced CD86+ cell numbers in periodontal tissues compared to those with C3ar+/+ and C3ar+/− genotypes." (PMID 40240339, 2025). "Both M1 (CD68 + CD86+) and M2 (CD68 + CD206+) macrophages were increased in gingiva with periodontitis compared to healthy gingiva, which confirmed the results of IHC." (PMID 38689292, 2024). "To confirm the presence of macrophages, we also examined the expression of the macrophage markers CD14, CD68, CD86, and CD163 in gingival biopsies from periodontally healthy individuals and periodontitis patients." (PMID 33513808, 2021). "The presence of macrophage markers CD14, CD86, CD68, and CD163 was examined in gingival biopsies from healthy individuals and periodontitis patients." (PMID 33513808, 2021). "Similarly, CD86, a critical co-stimulatory molecule involved in T-cell activation, and PTPRC (CD45), a regulator of immune cell signaling, underscore the immune involvement in periodontitis." (PMID 41140666, 2025).
chronic lymphocytic leukemia (8 papers, 2014 to 2024). "It significantly decreased tumor proliferation and expression of surface activation markers CD69 and CD86 in chronic lymphocytic leukaemia which has similar clinical manifestations to MCL." (PMID 32685149, 2020). "This study compares immune factors like PD-1/PD-L1, CTLA-4/CD86, CD200R/CD200, and EBV in chronic lymphocytic leukemia (CLL, a SID) and common variable immunodeficiency (CVID, a PID)." (PMID 37835480, 2023). "Indeed, an increased expression of both CD86 and CD80 in response to TLR9 stimulation was shown in chronic lymphocytic leukemia, but not in response to TLR7 stimulations." (PMID 29805758, 2018).
Crohn disease (8 papers, 2012 to 2024). A gastrointestinal disorder characterized by chronic inflammation involving all layers of the intestinal wall, noncaseating granulomas affecting the intestinal wall and regional lymph nodes, and transmural fibrosis. "Both lean and Crohn’s disease visceral ASCs expressed equivalent surface percentages of the antigen-presenting molecules human leucocyte antigen—DR isotype (HLA-DR) and CD86." (PMID 33924264, 2021). "In addition, inflammatory macrophages and activated DCs (CD86 + PDL1+) were found to be specifically enriched in inflamed ileum of Crohn’s disease patients." (PMID 31718550, 2019). "CD80 and CD86 were induced by most probiotic strains in ulcerative colitis (UC) patients whereas only B. bifidum induced CD80 and CD86 expression in Crohn’s disease (CD) patients." (PMID 32872480, 2020). "Interestingly, both lean and Crohn’s disease VAT-derived ASCs expressed equivalent surface percentages of antigen-presenting molecules HLA-DR and CD86, and presented similar MFI values for these markers." (PMID 33924264, 2021). "The Newcastle University RA (Dex + Vit D3) and the Crohn’s disease (Dex) trials both reported decreased CD83 expression, high CD86 expression, decreased IL-12 secretion, and elevated IL-10 secretion in their tDC products suggesting a possible tDC shared phenotype." (PMID 29075262, 2017). "Similarly, immunohistochemistry analysis in Crohn’s disease and ulcerative colitis patients showed the levels of activation markers like CD83 and CD86 expressed on DCs, primarily mDCs, were significantly higher in inflamed mucosa from patients compared with non-inflamed mucosa and healthy controls." (PMID 38448477, 2024). "Tol-DCs generated from Crohn’s disease patients showed a statistically significant impairment in the upregulation of CD80, CD83 and HLA-DR compared to iDCs, with no CD86 modification." (PMID 23300676, 2012).
HIV-1 infection (8 papers, 2012 to 2024). The type species of lentivirus and the etiologic agent of acquired immunodeficiency syndrome (AIDS). "Rab11 has been implicated in the deployment of the T cell co-stimulatory molecules CD80 and CD86 from the cell surface of monocytes, during HIV-1 infection." (PMID 27005655, 2016). "The proportion of inflammatory monocytes expressing CD86 tended to be greater in untreated HIV-1 infection (p = 0.050) and the MFI of CD86 on these cells was greater in patients than among controls (p = 0.004)." (PMID 26430882, 2015). "In summary, we have identified distinct perturbations in circulating monocyte phenotypes in patients with untreated HIV-1 infection: elevated expression of HLA-DR and CD86 that normalized with ART while expression of the chemokine receptors CX3CR1 and CCR2 rose with ART." (PMID 26430882, 2015). "In untreated HIV-1 infection, circulating monocytes have greater expression of HLA-DR and CD86 that may reflect in vivo activation and might affect their ability to co-stimulate T cells." (PMID 26430882, 2015). "Both the proportion of CD86 expressing traditional monocytes and the density of CD86 on traditional monocytes were significantly higher in untreated HIV-1 infection compared to the levels seen in the healthy control population (p = 0.008, p = 0.009 respectively)." (PMID 26430882, 2015). "We found an upregulation of pro-inflammatory markers, i.e., HLA-DR, CD38, CD86, and CD80, during early HIV-1 infection stage in several organs, which persisted into the late infection stages." (PMID 39575258, 2024). "Upon HIV-1 infection, the basolateral detached DCs exhibit a semi-mature phenotype as evident from upregulation of activation marker CD83 and to a lesser degree CD86." (PMID 39729509, 2024). "Surface CD86 expression in HIV-1 infected DCs increased at 5 and 7 dpi compared with that of mock-infected DCs, suggesting that HIV-1 infection induced DC maturation." (PMID 22479639, 2012). "Of note, differential modulation of CD86 and DC-SIGN expression in DCs was observed between lentiviral transduction and WT HIV-1 infection." (PMID 22479639, 2012).